EPB41L4A-DT (EPB41L4A divergent transcript)
Synonyms: FLJ11235; EPB41L4A-AS2
Gene: Long non-coding RNA gene on chromosome 5 (112,419,583 to 112,420,978, forward strand). Ensembl gene ENSG00000278921.
Diseases named in the same sentence as EPB41L4A-DT in open-access papers:
EPB41L4A-DT is named in the same sentence as 1 disease in open-access papers, as found by Europe PMC text mining. Sharing a sentence is not in itself a finding about the gene and the disease.
EPB41L4A-DT shares sentences with these, for which no sentence is quoted: cancer (1 paper).